CDH1 (cadherin 1)
Diseases named in the same sentence as CDH1 in open-access papers (continued):
Sharing a sentence is not in itself a finding about the gene and the disease.
breast carcinoma (continued). "It has been suggested that EZH2 enforces the silencing of E-cadherin in basal breast cancers and BRCA1-deficient tumors, and promotes the mesenchymal cell states of these carcinoma cells by driving H3K27me3 that is associated with the CDH1 promoter." (PMID 33572395, 2021). "For instance, CDH1 is not only associated with increased breast cancer risk, but also a predisposition to gastric cancer." (PMID 33959510, 2021). "The associated cancer phenotype in heterozygous carriers of germline pathogenic variants in CDH1 reflects a loss of function of E-cadherin, with increased risks of diffuse subtypes of gastric cancer, and/or lobular subtypes of breast cancer." (PMID 34771713, 2021). "An unexpectedly high number of early-onset diffuse gastric and lobular breast cancer in apparently unrelated families carrying the same CDH1 c.1901C>T variant (formerly known as missense p.A634V) in Northern Portugal suggested a founder effect in this region." (PMID 34503274, 2021). "Clinically, an association between CDH1 methylation and breast cancer progression has also been reported." (PMID 32301282, 2020). "E-cadherin inactivation by somatic mutation of the CDH1 gene drives development of lobular carcinoma in situ (LCIS) and ILBC." (PMID 32572153, 2020). "Cdh1 is also dysregulated in breast cancer and melanoma, causing an impairment in genome stability and DNA damage response." (PMID 32882786, 2020). "CDH1-mutated breast cancer cells are sensitive to ROS1 tyrosine kinase inhibitors including foretinib or crizotinib." (PMID 33004031, 2020). "The review strategy was to find the articles which showed a relation between the CDH1 mutation and gastric and breast cancer as well as colorectal carcinoma." (PMID 33062523, 2020). "Of the three known single nucleotide polymorphisms (SNP) of CDH1, rs850805755, rs852280880 and rs852639930, rs850805755 and rs852280880 were associated with a decreased risk and a later onset of mammary tumor development." (PMID 33076339, 2020). "According to the report, miR-9 targets CDH1, the E-cadherin-encoding mRNA, which is related to increased cell motility and invasiveness and metastasis in breast cancers." (PMID 31783700, 2019). "Although CRM1 knockdown or inhibiting CRM1 using Leptomycin B did not affect Cdh1 expression, a significant enrichment of Cdh1 in the nuclear fraction was observed in CRM1-deficient breast cancer cells." (PMID 31420536, 2019). "Depleting Cdh1 accelerates breast cancer cell proliferation and cooperates with PTEN loss to promote breast tumor progression in mice." (PMID 31420536, 2019). "There were 495 TAC mRNA abundance changes associated with CDH1 mutations in patients with luminal A breast cancer." (PMID 31308365, 2019).
breast carcinoma (continued). "The prophylactic surgery procedure has been demostrated to confer survival benefits in CDH1 mutation carriers even if it doesn’t completely eliminate breast cancer risk." (PMID 31028995, 2019). "Four SNPs [rs3218550 (XRCC2), rs6917 (PHB), rs1801516 (ATM), and rs13689 (CDH1)] were significantly associated with risk of breast cancer." (PMID 29433565, 2018). "We also showed that the association of the A allele of CDH1 -160C/A SNP with breast cancer metastasis is statistically significant." (PMID 29285016, 2017). "We found that CDH2, 4, 6, and 17 were frequently amplified/overexpressed in breast cancer while CDH1 was downregulated/mutated." (PMID 28392805, 2017). "For example, in the case of breast cancer the lobular phenotype is associated with deletions in the CDH1 gene (encoding E-cadherin) and the mesenchymal/metaplastic features are predictive in the case of AR-positive triple negative breast cancers." (PMID 28523274, 2017). "The present study was directed to assess the role of -160 C/A CDH1 SNP as a possible risk factor in breast cancer and the association of this polymorphism with clinical and laboratory findings of BC patients in an Iranian population." (PMID 29285016, 2017). "The CDH1 -160 C/A polymorphism is correlated with clinicopathologial findings of breast cancer patients." (PMID 29285016, 2017). "The present study was aimed to evaluate the possible role of CDH1 -160 C/A polymorphism as a potential risk factor for breast cancer in Kurdish population." (PMID 29285016, 2017). "In conclusion, our results show CDH1 -160 C/A is associated with increased breast cancer risk in Kurdish women." (PMID 29285016, 2017). "Using CDH1 to query the breast cancer network, we associated the gene to its well-established role in cell adhesion." (PMID 27836980, 2017). "Mutations in high-risk breast cancer genes or genes associated with syndromic diagnoses (CDH1, PALB2, PTEN, STK11, and TP536, 20, 21) were identified in 1.4% of the FBC cohort." (PMID 28649662, 2017). "Germline mutations in CDH1 are associated with an increased risk of gastric and breast cancer, and CDH1 somatic inactivation via epigenetic silencing or truncating mutations is common in both cancer types." (PMID 28115009, 2017). "In the present study we showed significant association between CDH1 -160C/A polymorphism and breast cancer risk in Kurdish women." (PMID 29285016, 2017). "Apart from diffuse gastric and lobular breast carcinomas where germline mutations and somatic inactivation of the E‐cadherin (CDH1) locus occurs, different studies have supported E‐cadherin detection as a diagnostic marker in several tumor types." (PMID 28590039, 2017). "This suggested that our data-driven approach effectively identified the specific subunits of the adherens junction complex whose expression is reduced by CDH1 mutation in breast cancer." (PMID 29032073, 2017). "The results implied a conspicuously significant relationship between the CDH1 -160C/A polymorphism and breast cancer risk under the dominant genetic model (AA + CA vs. CC, OR = 1.207, P = 0.019)." (PMID 27349965, 2016). "Numerous epidemiological studies have evaluated the association between the CDH1 -160C/A polymorphism and the risk of breast cancers." (PMID 27349965, 2016). "It was found that the CDH1 -160C/A polymorphism was significantly associated with breast cancer risk in the dominant model (CA + AA vs. CC: OR = 1.207, 95 % CI = 1.031–1.412, P = 0.019)." (PMID 27349965, 2016). "After critically reviewing the five studies on the CDH1 -160C/A polymorphism (1344 cases total, 1569 control), we performed a comprehensive assessment to investigate the significance of CDH1 -160C/A in breast cancer pathogenesis." (PMID 27349965, 2016).
breast carcinoma (continued). "In the present study, the relationship between the CDH1 -160C/A polymorphism and breast cancer risk was analyzed." (PMID 27349965, 2016). "In regards to breast cancer, few investigations have been carried out on the association between CDH1 polymorphisms and cancer severity or progression." (PMID 27852262, 2016). "CDH1 mutations are characteristically present in families with predisposition to gastric cancer, however breast cancer frequently co-occurs." (PMID 27067391, 2016). "Downregulation of E-cadherin in breast cancer is associated with aberrant DNA methylation of the CDH1 gene promoter and/or repression by mesenchymal transcription factors that are known to cause promoter methylation." (PMID 26901232, 2016). "Subsequent studies of families with CDH1 mutations led to similar conclusions: in four families with a total of 22 breast cancers, all invasive tumors for which a pathological report was available were lobular." (PMID 25848941, 2015). "miR-9 can promote the motility and invasiveness of breast cancer cells by targeting CDH1, the E-cadherin-encoding messenger RNA." (PMID 26146543, 2015). "In women, loss or down-regulation of CDH-1 in breast carcinoma is associated with shorter survival time." (PMID 26370564, 2015). "For example, the CDH1 gene encoding E-cadherin is frequently hypermethylated in breast cancer cell lines exhibiting an EMT-like phenotype and is also shown to be methylated along with several other genes silenced in basal-like breast cancers." (PMID 24840099, 2014). "The loss or downregulation of CDH1, the E-cadherin gene located on 16q22.1, is implicated in breast cancer invasion and proliferation." (PMID 23717195, 2013). "More research is required in order to describe the role of CDH1 mutations in Chinese at high risk of breast cancer." (PMID 23318652, 2013). "ILBC is a special breast cancer entity associated with mutational CDH1 inactivation and loss of E-cadherin expression." (PMID 24023670, 2013). "miR-9, which is upregulated in breast cancer cells, directly targets CDH1, the E-cadherin-encoding messenger RNA, and also promotes cell motility and invasiveness." (PMID 24212663, 2011). "Invasive and in situ lobular carcinomas confer similar genetic gains and losses, often bearing the same mutations in the gene that encodes E-cadherin (CDH1)." (PMID 21827679, 2011). "Cluster 2B (‘Epithelial-CDH1-mutated’) includes all breast cancer cell lines harbouring inactivating CDH1 mutations (MDA-MB-134VI, SK-BR-3, SK-BR-5, SUM44PE and OCUB-F) and two cell lines with wild-type CDH1, SUM185PE and Du4475." (PMID 16495925, 2006). "In this particular subset of high risk of breast cancer, 31 tumors showed low E-cadherin levels and CDH1 hypermethylation was detected in 21 of them (68%)." (PMID 16512896, 2006). "In this study, we reported aberrant methylation of the 5'CpG island of the CDH1 gene associated with reduced levels of E-cadherin expression in breast cancer." (PMID 16512896, 2006). "CDH1 mutations were also identified in lobular carcinoma in situ, the putative precursor of invasive lobular carcinoma." (PMID 16495925, 2006). "Notably, among breast cancer subtypes, loss of CDH1 expression is characteristic only of lobular carcinoma, whereas the majority of ductal carcinomas and their metastases retain CDH1 expression." (PMID 41459333, 2026). "Notably, a stop-gained variant in the CDH1 gene (Canine: p.Glu761*) is known to act as “pathogenic” in human breast cancer (Human: p.Glu758*)." (PMID 41168812, 2025).
breast carcinoma (continued). "CDH1 (encoding E-cadherin) is frequently mutated or lost in cancers, including breast cancer." (PMID 40740860, 2025). "Furthermore, no co-occurrence of BRCA1 or BRCA2 variants was found, suggesting that CDH1 variants contribute independently to hereditary breast cancer risk." (PMID 40366456, 2025). "Additionally, the presence of gastric cancer in the patient’s elder brother and breast cancers in two elder sisters aligns with the phenotype associated with CDH1 mutation." (PMID 40236650, 2025). "Understanding and addressing CDH1 loss at every level-from molecular biology to clinical management-has the potential to greatly improve outcomes for patients with this under-recognized subtype of breast cancer." (PMID 40757085, 2025). "This could be attributed to the fact that PIK3CA and RUNX1 mutations are commonly observed in luminal-type breast cancer; in the intrinsic subtype, CDH1-altered ILC exhibited a higher proportion of luminal-type cases." (PMID 39201647, 2024). "Loss of CDH1 is also strongly related to breast cancer progression in patients." (PMID 37885030, 2023). "This study demonstrates the complexities of breast cancer risk associated with HLBC due to germline CDH1 P/LP variants, including both the natural history of this disease as well as the demographic, pathologic, and radiographic characteristics seen in this patient population." (PMID 37758801, 2023). "Deficiency of CDH1 is closely related to breast cancer metastasis." (PMID 37885030, 2023). "Excluding six organoids for which polyclonal origins were suspected and another with a germline CDH1 mutation, we finally evaluated somatic mutations for 64 organoids established from six pre- (n = 20) and nine postmenopausal (n = 32) patients with breast cancer and 12 from six healthy women." (PMID 37495687, 2023). "The heritable CDH1 mutations are associated with an increased risk of gastric and breast cancers." (PMID 37716978, 2023). "CDH1 has also been implicated in stem cell-like properties of breast cancer." (PMID 36810560, 2023). "In addition, transcriptional silencing of CDH1 was associated with the EMT in human breast cancer cells." (PMID 36315446, 2022). "Because CDH1 pathogenic variants could be associated with breast cancer (BC) susceptibility, CDH1 rearrangements could also impact it." (PMID 36553480, 2022). "The invasiveness of breast cancer cells depends on the activity of transcription factors that modulate the expression of cell adhesion proteins, such as E-cadherin, encoded by the CDH1 gene and N-cadherin, encoded by the CDH2 gene, and the epithelial-to-mesenchymal transition." (PMID 35163478, 2022). "Among all CDH family members, CDH1/2/3/4/7/9/10/11/12/13/15/16/26 were significantly positively associated with a lower DMFS, and CDH1/2/4/6/7/11/12/13/15/22/23/24 mRNA expression levels were higher in breast cancer than in normal tissues in the Oncomine database." (PMID 36315446, 2022). "The lifetime risk of breast cancer in the CDH1 mutation carriers ranges from 40% to 50%." (PMID 36551262, 2022). "Some studies suggest that elevated β-catenin levels in breast cancer could be partially due to loss of Cadherin 1 (CDH1), a frequently observed feature in advanced and invasive tumors." (PMID 35663403, 2022). "Furthermore, results of the bc-GenExMiner database demonstrated that increased CDH4/12/13 expressions were associated with basal-like breast cancer, and increased CDH1/2/11 expressions suggested a high SBR grade status in patients." (PMID 36315446, 2022). "In addition, patients harbouring CDH1 variants in the linker region (regions shown in white) were significantly less likely to develop breast cancer." (PMID 34949788, 2022).
breast carcinoma (continued). "Among the genes located on chromosome 16q, the CDH1 gene, encoding for the cell adhesion glycoprotein E-cadherin, has been repeatedly implicated as an important player in mediating the effect of 16q-loss in breast cancer." (PMID 33808143, 2021). "In this study, the remaining pathogenic variants in breast cancer occurred in CDH1 and MUTYH." (PMID 33827469, 2021). "The loss of CDH1/E-cadherin, a key factor associated with epithelial differentiation and cell adhesion, is a hallmark of malignant progression for many cancers including breast cancer." (PMID 33671920, 2021). "To determine whether increased VE-cadherin expression in TCs is responsible for the downregulation of E-cadherin and cadherin-11, we transduced breast cancer cell lines with a VE-cadherin–GFP-encoding lentiviral vector." (PMID 32752204, 2020). "Mutations in the CDH1 (Cadherin 1 gene) were also more common among older-onset breast tumours, and are related to increased proliferation, invasion, and metastasis of some cancer types, including breast cancer." (PMID 32164620, 2020). "Similarly, another haplotype-based study conducted to investigate the association of CDH1 with susceptibility to breast cancer in the Chinese Han population, reported that rs13689 was associated with increased risk of breast cancer and poor survival." (PMID 29433565, 2018). "Although atypical lobular hyperplasia and lobular carcinoma in situ are considered markers of increased risk of sporadic invasive lobular carcinoma, their roles and characteristics in invasive lobular carcinoma in CDH1 germline mutation carriers have rarely been studied." (PMID 30568591, 2018). "Spalt like transcription factor 1 (SALL1) encodes a zinc finger transcriptional repressor, which has recently been identified as a tumor suppressor gene, whose expression was in positive correlation with CDH1 and associated with the survival of patients in breast cancer." (PMID 30233644, 2018). "The frequencies of prognostically favorable PIK3CA and CDH1 mutations were lower in women of African ancestry than in Whites, which may reflect differences in breast cancer risk factors across populations." (PMID 30327465, 2018). "Indeed, inactivating mutations of the CDH1 gene in gastric and lobular breast cancers have defined E-cadherin as a tumor suppressor for these cancer types." (PMID 28750639, 2017). "The A allele of CDH1 -160 C/A may be a risk factor for progression of breast cancer in Kurdish patients." (PMID 29285016, 2017). "Women with a constitutional CDH1 mutation are at elevated risk for breast cancer." (PMID 29287594, 2017). "They suggested that the CDH1 -160C/A polymorphism may be proposed as a genetic risk factor for breast cancer in south Indian women." (PMID 29285016, 2017). "Recently, a meta-analysis depicted that CDH1 -160 C/A SNP might contribute to breast cancer susceptibility." (PMID 29285016, 2017). "In conclusion, these data provided further evidence that the CDH1 -160C/A polymorphism may represent a risk factor for breast cancer development." (PMID 27349965, 2016). "Additionally, promoter hypermethylation of the CDH1 gene is positively associated with EMT in breast cancer cell lines, corresponding with the increased potential for invasion and metastasis observed in these cells." (PMID 26905733, 2016). "Then, the association between CDH1 -160C/A SNP and breast cancer risk was analyzed." (PMID 27349965, 2016).